ARL10 (ARF like GTPase 10)
Synonyms: ARL10A
Tractability: PROTAC: ubiquitination databases record sites on it; its protein half-life has been measured.
Gene: Protein-coding gene on chromosome 5 (176,365,487 to 176,401,865, forward strand). Ensembl gene ENSG00000175414.
Gene Ontology:
Molecular function: GTP binding; GTPase activity
Cellular component: mitochondrion
Genetic constraint (gnomAD): Loss-of-function variants: 25 observed, 22.94 expected, observed/expected ratio (o/e) 1.09, 90% interval 0.79 to 1.52. The upper end of that interval is the gene's LOEUF score, 1.52, which puts it in group 6 of 6, group 1 being the genes least tolerant of losing a copy. Missense variants: 281 observed, 287.88 expected, observed/expected ratio (o/e) 0.98, 90% interval 0.88 to 1.08. Synonymous variants: 129 observed, 128.01 expected, observed/expected ratio (o/e) 1.01, 90% interval 0.87 to 1.17.
Homologues: Orthologues: chimpanzee ARL10 (99% identical), macaque ARL10 (98% identical), dog ARL10 (94% identical), guinea pig ARL10 (93% identical), pig ARL10 (93% identical), rat Arl10 (88% identical), mouse Arl10 (88% identical), zebrafish arl10 (39% identical), tropical clawed frog arl10 (32% identical). Paralogues in human: ARL9 (30% identical), TRIM23 (28% identical), ARF6 (26% identical), ARF1 (25% identical), ARF4 (25% identical), ARL1 (25% identical), ARF3 (25% identical), ARF5 (25% identical), ARL3 (24% identical), ARL2 (23% identical), ARL11 (23% identical), ARL5A (23% identical), and 18 more.
Diseases named in the same sentence as ARL10 in open-access papers:
ARL10 is named in the same sentence as 4 diseases in open-access papers, as found by Europe PMC text mining. Sharing a sentence is not in itself a finding about the gene and the disease. The quoted sentences say what the papers report.
endometrial cancer (1 paper, 2022). Primary or metastatic malignant neoplasm involving the endometrium (mucous membrane that lines the endometrial cavity). "In the case of the ADP-ribosylation factor (ARF)/ARF-like protein (ARL) family, it was observed that a high expression of ARL4D, ARL1, ARF1, and SAR1B in endometrial cancer is associated with better prognosis, while a high expression of ARL4C, ARL2, ARL10, ARL16, and ARL14 promotes worse survival." (PMID 35163161, 2022).
tumours (1 paper, 2026). "RT-qPCR confirmed elevated levels of miR-1271-5p and ARL10 in ccRCC tumours and increased circulating miR-1271-5p in patient plasma." (PMID 41998206, 2026).
ARL10 also shares sentences with these, for which no sentence is quoted: clear cell renal cell carcinoma (1 paper); neuromuscular disease (1).